SMTNL1 (smoothelin like 1)
Description:
Plays a role in the regulation of contractile properties of both striated and smooth muscles. When unphosphorylated, may inhibit myosin dephosphorylation. Phosphorylation at Ser-299 reduces this inhibitory activity (By similarity).
Synonyms: CHASM
Tractability: No criterion of Open Targets' tractability assessment is met for any kind of drug.
Gene: Protein-coding gene on chromosome 11 (57,537,595 to 57,550,272, forward strand). Ensembl gene ENSG00000214872.
Subcellular location: Cytoplasm, myofibril; Cytoplasm, myofibril, sarcomere, I band; Cytoplasm, myofibril, sarcomere, M line; Nucleus
Gene Ontology:
Molecular function: calmodulin binding; CH domain binding; disordered domain specific binding; protein phosphatase 1 binding; tropomyosin binding
Biological process: actin cytoskeleton organization; positive regulation of vasoconstriction; negative regulation of DNA-templated transcription
Cellular component: contractile muscle fiber; cytoplasm; nucleus; I band; M band; myofibril
Genetic constraint (gnomAD): Loss-of-function variants: 41 observed, 47.14 expected, observed/expected ratio (o/e) 0.87, 90% interval 0.68 to 1.13. The upper end of that interval is the gene's LOEUF score, 1.13, which puts it in group 4 of 6, group 1 being the genes least tolerant of losing a copy. Missense variants: 591 observed, 633.42 expected, observed/expected ratio (o/e) 0.93, 90% interval 0.87 to 1. Synonymous variants: 234 observed, 238.42 expected, observed/expected ratio (o/e) 0.98, 90% interval 0.88 to 1.09.
Homologues: Orthologues: chimpanzee SMTNL1 (98% identical), macaque SMTNL1 (94% identical), dog SMTNL1 (70% identical), rabbit SMTNL1 (66% identical), rat Smtnl1 (63% identical), mouse Smtnl1 (63% identical), guinea pig SMTNL1 (58% identical), tropical clawed frog syne2.2 (35% identical), Drosophila melanogaster Ehbp1 (12% identical). Paralogues in human: MICALL1 (16% identical), MICALL2 (15% identical), EHBP1 (14% identical), EHBP1L1 (12% identical), ASPM (11% identical), GAS2L1 (5% identical), GAS2 (3% identical).
Diseases named in the same sentence as SMTNL1 in open-access papers:
SMTNL1 is named in the same sentence as 16 diseases in open-access papers, as found by Europe PMC text mining. Sharing a sentence is not in itself a finding about the gene and the disease. The quoted sentences say what the papers report.
Insulin resistance (2 papers, 2021 to 2024). Increased resistance towards insulin, that is, diminished effectiveness of insulin in reducing blood glucose levels. "In addition, SMTNL1-/- mice have impaired glucose tolerance associated with pronounced insulin resistance." (PMID 34675885, 2021). "SMTNL1 enhances the differentiation of endometrial epithelial cells in a progesterone-dependent manner and prevents cellular transformation during insulin resistance." (PMID 38883605, 2024). "Collectively, these data demonstrated that pregnancy and hyperinsulinemia/hyperglycemia modeling gestational diabetes induced insulin resistance, and the overexpression of SMTNL1 attenuated this effect." (PMID 38883605, 2024). "In mouse and differentiated skeletal muscle cell culture models of insulin resistance, SMTNL1 can attenuate the effects of altered IRS-1 serine phosphorylation induced by the over-activation of Ser/Thr protein kinases." (PMID 38883605, 2024). "We show that SMTNL1 promotes the differentiation of endometrial epithelial cells in a progesterone-dependent manner to attenuate insulin resistance." (PMID 38883605, 2024). "SMTNL1 overexpression prevented the metabolic shift of SKM during insulin resistance induced by supraphysiological TH levels." (PMID 34675885, 2021). "Collectively, these data provide evidence that T3 excess triggers the development of insulin resistance while overexpression of SMTNL1 can moderate these effects." (PMID 34675885, 2021). "One potential regulator of insulin resistance in SKM is the smoothelin-like protein 1 (SMTNL1)." (PMID 34675885, 2021). "These lines of evidence suggest that SMTNL1 potentially prevents hyperthyroidism-induced changes in SKM, and it holds great promise as a novel therapeutic target in insulin resistance." (PMID 34675885, 2021).
Cerebral arteriovenous malformation (1 paper, 2020). "The gene expression of SMTNL1 was also significantly increased by approximately 4-fold in human cerebral arteriovenous malformations, suggesting that the elevated level of SMTNL1 may decrease MYPT1 expression to relax brain blood vessels and thus contribute to this lumen disorder." (PMID 32478077, 2020).
gestational diabetes (1 paper, 2024). Carbohydrate intolerance first diagnosed during pregnancy. "Furthermore, SMTNL1 hampers the migration capacity of epithelial cells in a gestational diabetes model by inhibiting the expression of MYPT1, the regulatory subunit of MP, and the activity of the holoenzyme, resulting in increased phosphorylation of the 20 kDa regulatory myosin light chain." (PMID 38883605, 2024). "SMTNL1 may have therapeutic relevance to the progesterone-dependent inhibition of endometrial epithelial cell migration under hyperglycemic conditions and insulin sensitivity in the endometrium in gestational diabetes or other metabolic disorders." (PMID 38883605, 2024). "Therefore, SMTNL1 may be a feasible therapeutic target for progesterone-dependent inhibition of endometrial epithelial cells during hyperglycemia and insulin-sensitizing endometrium in gestational diabetes or other metabolic disorders." (PMID 38883605, 2024). "SMTNL1 also acts as an insulin-sensitizing agent by increasing the gene expression of PP2A and DUPS9 protein phosphatases, resulting in decreased ERK1/2 activity and, hence, decreasing the phosphorylation of IRS-1 at Ser612 under gestational diabetes conditions." (PMID 38883605, 2024).
Hyperglycemia (1 paper, 2024). An increased concentration of glucose in the blood. "Our data suggests that SMTNL1 reduces the expression of MYPT1, the regulatory subunit of MP, in the presence of progesterone, and these changes are more prominent in the presence of progesterone and hyperglycemia." (PMID 38883605, 2024).
hyperthyroidism (1 paper, 2021). Overactivity of the thyroid gland resulting in overproduction of thyroid hormone and increased metabolic rate. "In this study, we characterize the role of SMTNL1 in the molecular mechanism of hyperthyroidism in human skeletal muscle and the effect of supraphysiological T3 exposure on differentiated C2C12 muscle cells." (PMID 34675885, 2021). "The involvement of SMTNL1 in hyperthyroidism-induced posttranslational alterations was determined using Western blot analyses of NT-FT-SMTNL1-transfected and/or T3-treated myotubes." (PMID 34675885, 2021). "SMTNL1 is the major metabolic regulator in SKM and SMTNL1 KO mice mimic the pathophysiological processes of hyperthyroidism." (PMID 34675885, 2021). "SMTNL1 expression decreased 6-fold in the hyperthyroid samples, indicating that SMTNL1 may play a role in the pathophysiology of hyperthyroidism in SKM." (PMID 34675885, 2021). "The overexpression of SMTNL1 or an SMTNL1-mimicking membrane-permeable peptide might counteract the effects of hyperthyroidism selectively in SKM, promoting insulin-sensitizing effects and maintaining the homeostasis of SKM." (PMID 34675885, 2021).
Sepsis (1 paper, 2011). Sepsis is defined as life-threatening organ dysfunction caused by a dysregulated host response to infection. "Current evidence supports a key role for SMTNL1 in adaptive responses to physiological stresses (e.g., pregnancy, exercise and sepsis)." (PMID 21352594, 2011).
type 2 diabetes mellitus (1 paper, 2024). A type of diabetes mellitus that is characterized by insulin resistance or desensitization and increased blood glucose levels. "SMTNL1 null mice exhibit reduced reproductive fitness and are more prone to type 2 diabetes mellitus." (PMID 38883605, 2024).
neoplasia (2 papers, 2017 to 2024). "The presence of enriched sgRNA targeting Smtnl1 in C2 could indicate a potential for increased tumor metastasis." (PMID 39605490, 2024).
SMTNL1 also shares sentences with these, for which no sentence is quoted: adenocarcinoma of the breast (1 paper); adenocarcinoma of the lung (1); astrocytoma of the brain (1); endometrial adenocarcinoma (1); Hyperinsulinemia (1); Impaired glucose tolerance (1); metabolic disorders (1); metabolic syndrome (1).